FIRRE (firre intergenic repeating RNA element)
Synonyms: LINC01200
Gene: Long non-coding RNA gene on chromosome X (131,688,779 to 131,830,928, reverse strand). Ensembl gene ENSG00000213468.
Gene Ontology:
Molecular function: DNA-DNA tethering activity
Biological process: chromatin organization
Diseases named in the same sentence as FIRRE in open-access papers:
FIRRE is named in the same sentence as 13 diseases in open-access papers, as found by Europe PMC text mining. Sharing a sentence is not in itself a finding about the gene and the disease. The quoted sentences say what the papers report.
colorectal cancer (2 papers, 2022 to 2024). A primary or metastatic malignant neoplasm that affects the colon or rectum. "Overexpression of FIRRE promotes diffuse large B-cell lymphoma, and colorectal cancer." (PMID 38556083, 2024).
diffuse large B-cell lymphoma (2 papers, 2021 to 2024). "Besides, FIRRE is transcriptionally regulated by MYC and contributes to the proliferation and anti-apoptosis of diffuse large B-cell lymphoma (DLBCL) cells via the Wnt/β-catenin pathway." (PMID 34093813, 2021).
sarcoma (1 paper, 2022). A usually aggressive malignant neoplasm of the soft tissue or bone. "Here, we found that SNHG1, FIRRE, and YEATS2-AS1 could serve as biomarkers to predict overall survival of sarcoma patients, which provides a new insight into treatment of STS." (PMID 35669241, 2022).
Sotos syndrome (1 paper, 2023). Sotos syndrome is a rare multisystemic genetic disorder characterized by a typical facial appearance, overgrowth of the body in early life with macrocephaly, and mild to severe intellectual disability. "The host gene for this molecule is FIRRE, a lncRNA that has been linked to Sotos syndrome, among conditions." (PMID 37373172, 2023).
cancer (3 papers, 2021 to 2022). A tumor composed of atypical neoplastic, often pleomorphic cells that invade other tissues. "Interchromosomal interactions have been demonstrated between SOX9 and the lncRNA CISTR-ACT gene or the ATF4 and FIRRE genes to serve biological processes including mammalian development and differentiation, as well as cancer stemness." (PMID 34707247, 2022).
FIRRE also shares sentences with these, for which no sentence is quoted: colon cancer (1 paper); esophageal cancer (1); gastric carcinoma (1); hepatocellular carcinoma (1); infection (1); myeloma (1); non-small cell lung carcinoma (1); ovarian carcinoma (1).